FTO (FTO alpha-ketoglutarate dependent dioxygenase)
Diseases named in the same sentence as FTO in open-access papers (continued):
Sharing a sentence is not in itself a finding about the gene and the disease.
colon carcinoma (35 papers, 2009 to 2026). "A close connection was reported between FTO genotype and the risk of various cancers risk such as colon cancer." (PMID 36263301, 2022). "In colon cancer cells, FTO overexpression causes a corresponding boost in PD‐L1 protein expression in an IFN‐γ‐dependent manner." (PMID 34586737, 2021). "Fat mass and obesity-associated protein (FTO) demethylates m6A, depleting FTO downregulated IFN-γ-induced PD-L1 expression in colon cancer." (PMID 34088360, 2021). "Therefore, FTO, as a molecule significantly associated with metabolism, can affect the level of energy metabolism, especially glycolysis, in colon cancer." (PMID 39820532, 2025). "Dietary fiber may play a role in preventing colon cancer in people with FTO gene risk allele." (PMID 36263301, 2022). "The protein expression of PKM2 and the intensity of fluorescence staining in the nucleus of PKM2 were detected to be increased in colon carcinoma cells with over-expression of FTO." (PMID 39820532, 2025). "The results revealed a significant elevation of FTO expression in various tumor tissues compared to adjacent tissues, a trend also observed in colon cancer." (PMID 39820532, 2025). "The observation was confirmed by detecting FTO expression at protein and mRNA levels in five colon cancer cells and one normal colon epithelial cell." (PMID 39820532, 2025). "To ascertain the correlation between the two, we used western blot analysis to test the expression of PKM2 in colon cancer cells that overexpressed FTO or had FTO knocked down." (PMID 39820532, 2025). "The findings of our study indicate that the levels of FTO expression in colon cancer tissues were notably elevated compared to adjacent tissues." (PMID 39820532, 2025). "The TCGA database was utilized to analyze the expression of FTO in pan-cancer and colon cancer and conduct a more comprehensive examination of FTO expression in tumours." (PMID 39820532, 2025). "Conversely, the glycolytic capacity of colon cancer cells decreased in LOVO cells when FTO was suppressed, compared to the control empty vector." (PMID 39820532, 2025). "In vitro, the excessive expression of FTO in colon cancer cells stimulated proliferation as measured by the CCK-8 method." (PMID 39820532, 2025). "An upregulation of FTO was observed in colon cancer through data mining and analysis of pathological specimens." (PMID 39820532, 2025). "It has been demonstrated that FTO knockdown inhibited the proliferation of colon cancer cells corresponding to the empty vector." (PMID 39820532, 2025). "Subsequently, the upregulation of FTO led to the observation of increased migration and invasion of colon cancer cells." (PMID 39820532, 2025). "This investigation involved the examination of FTO expression in a total of 103 colon cancer tissue samples through the utilization of immunohistochemistry." (PMID 39820532, 2025). "The expression of FTO was notably higher in the five different colon cancer cells at both the protein and mRNA levels compared with the normal colon epithelial cells." (PMID 39820532, 2025). "In conclusion, the present study indicated that TTC7B inhibits colon cancer progression in an FTO-dependent manner both in vitro and in vivo." (PMID 39897037, 2025). "The results showed that overexpressing FTO enhanced the proliferation, migration, and invasion abilities of colon cancer cells, which consequently affected the malignant characteristics of these cells." (PMID 39820532, 2025). "The impact of FTO on colon cancer glycolysis has significant implications for colon proliferation, invasion, and metastasis, as it positively modulates the expression of PKM2." (PMID 39820532, 2025). "A notable augmentation in the expression of FTO was observed in individuals diagnosed with clinical stage 3 of colon cancer, as compared to those diagnosed with clinical stage 2 and individuals without cancer." (PMID 39820532, 2025).
colon carcinoma (continued). "Both PCIF1 and FTO have been found to be reduced in metastatic cancer cell lines, with FTO expression particularly low in patient-derived colon cancer cell lines." (PMID 39629934, 2025). "To elucidate the impact of energy metabolism on colon cancer, we investigated the expression of FTO using the Seahorse XF96 metabolic function analysis." (PMID 39820532, 2025). "Five colon cancer cell lines were employed to investigate FTO's biological function and examine the varying levels of FTO expression." (PMID 39820532, 2025). "In summary, this study revealed that FTO can affect aerobic glycolysis in colon cancer by influencing the expression level of PKM2, confirming the linkage between FTO and PKM2." (PMID 39820532, 2025). "Next, we evaluated the role of the FTO gene on the TTC7B-mediated inhibition of colon cancer cell proliferation using FTO-KO cell models." (PMID 39897037, 2025). "Our study investigates the correlation between FTO expression in colon cancer and clinicopathological characteristics using data from TCGA and UALCAN databases." (PMID 39820532, 2025). "For example, promoting FTO expression increases PD-L1 expression in colon cancer, whereas the knockdown of FTO suppresses PD-L1 expression levels." (PMID 39033180, 2024). "To further investigate the oncogenic role of FTO in colon cancer, we utilized a subcutaneous mouse model." (PMID 36874096, 2023). "For example, FTO-mediated upregulation of PD-L1 in colon cancer cells promotes immune escape, while inhibition of FTO sensitizes tumor cells to T-cell toxicity and overcomes hypomethylating agent-induced immune evasion." (PMID 35794625, 2022). "Deficiency of another m6A demethylase FTO decreases the mRNA and protein expression level of PDL1 in colon cancer cells." (PMID 36092891, 2022). "Our results were similar to that of a previous study which shows that FTO depletion inhibits the expression of PD-L1 in colon cancer cells through m6A modification." (PMID 35197058, 2022). "FTO enables to upregulate the PD‐L1 expression in colon cancer cells and subsequently promotes immune escape in the TIME." (PMID 34586737, 2021). "First, we show that FTO expression in colon cancer cells is finely regulated at the post-transcriptional level, though the precise underlying mechanism remains to be determined." (PMID 33741917, 2021). "Additionally, the prognostic evaluation conducted on colon cancer patients utilizing the TCGA database demonstrated that heightened FTO expression was correlated with a decreased survival rate." (PMID 39820532, 2025). "Thus, we established a model of colon cancer cell lines stably transfected with high and low expression of FTO in our study." (PMID 39820532, 2025). "The results also indicated that FTO overexpression could enhance the glycolysis level of colon cancer cells, and when underexpressed, it could reduce the glycolysis level of colon cancer cells." (PMID 39820532, 2025). "Moreover, the UALCAN database demonstrates a significant increase in FTO expression in colon cancer in comparison to normal tissue." (PMID 39820532, 2025). "Besides, we discovered that the impact of FTO on colon cancer glycolysis has significant implications for colon proliferation, invasion, and metastasis." (PMID 39820532, 2025). "Additionally, to validate the findings above within the database, an analysis was conducted to assess the expression of FTO within colon cancer tissues." (PMID 39820532, 2025). "Both FTO-KO and TTC7B-OE significantly inhibited the growth of LoVo cells in nude mice, and the loss of FTO abolished the effect of TTC7B-OE, suggesting a dominant effect of TTC7B over FTO on colon cancer cell proliferation." (PMID 39897037, 2025).
colon carcinoma (continued). "In vitro experiments utilized five human colon cancer cell lines and a normal colon epithelial cell line, with Western blotting and RT-PCR for protein and mRNA quantification, respectively, and lentiviral transfection to modulate FTO expression." (PMID 39820532, 2025). "They found that FTO is aberrantly expressed in colon cancer cell line (HCT-116)." (PMID 34571899, 2021). "However, the investigation of FTO in colon cancer remains limited." (PMID 39820532, 2025). "Furthermore, FTO expression was observed in colon cancer cells." (PMID 39820532, 2025). "In order to further explore the role of FTO in the aerobic glycolysis of colon cancer, we examined the expression of PKM2 in colon cancer cells using immunofluorescence staining about changes in FTO expression." (PMID 39820532, 2025). "Together, these results indicate not only that FTO plays an essential role in the inhibition of colon cancer cell proliferation by TTC7B but also that the TTC7B-mediated inhibition of cancer cell proliferation might be dependent on the demethylase activity of FTO." (PMID 39897037, 2025). "FTO is elevated in colon cancer and promotes glycolysis by modulating PKM2, which in turn affects the growth, invasion, and metastasis of colon cancer cells." (PMID 41311582, 2025). "Although FTO-KO (or FTO-OE) inhibited (or enhanced) colon cancer cell proliferation, unexpectedly, we found that TTC7B-OE, which upregulates FTO expression, inhibited cell proliferation in an FTO-dependent manner." (PMID 39897037, 2025). "TTC7B inhibited the proliferation of colon cancer cells by increasing the recruitment of RXRA to the FTO promoter, increasing FTO expression, and decreasing the total RNA m6A level." (PMID 39897037, 2025). "In this study, we found that FTO affects the glycolysis level of colon cancer cells primarily by adjusting the expression level of PKM2, which provides novel insights for colon cancer therapy." (PMID 39820532, 2025). "In colon cancer cell lines, METTL3 and RBM15 were downregulated, whereas transcript levels of FTO and ALKBH5 were upregulated." (PMID 38665783, 2024). "Altogether, these findings suggested that FTO has an important role in cell proliferation, tumor progression and m6A demethylation in the HCT116 colon cancer cell line." (PMID 36874096, 2023). "Depletion of FTO in human colon cancer cells markedly reduces the expression of both PD-L1 mRNA and protein in an IFN-γ signaling-independent manner, highlighting the positive role of FTO in PD-L1 regulation." (PMID 36810108, 2023). "Notably, after overexpression of FTO, the protein level of PKM2 in the colon cancer cell group increased than that of the empty group." (PMID 39820532, 2025). "In summary, we have shown that cytoplasmic FTO activity regulates m6Am modification of selected mRNAs and, subtly but surely, is necessary for maintaining the CSC phenotype in vitro and in vivo for human colon cancers." (PMID 33741917, 2021). "Among them, both two m6A Erasers (FTO and ALKBH5) were downregulated in colon cancer." (PMID 32993738, 2020). "We subsequently constructed an FTO luciferase reporter plasmid by inserting an FTO promoter fragment (2290 bp) and its RXRA binding motif-deleted mutant into the pGL3-basic vector and used the resulting plasmids to transfect HCT116, LoVo, and SW480 colon cancer cell lines." (PMID 39897037, 2025).
endometrial cancer (30 papers, 2011 to 2025). Primary or metastatic malignant neoplasm involving the endometrium (mucous membrane that lines the endometrial cavity). "In endometrial cancer (EC), higher FTO expression is closely linked to tumor metastasis and invasion." (PMID 39192357, 2024). "Variation in rs9939609, rs6499640, rs19079260, and rs8050136 in FTO genotype was associated with higher endometrial cancer risk." (PMID 35422475, 2022). "Clinically, FTO abundance is associated with poor prognosis and early relapse of endometrial cancer." (PMID 35409166, 2022). "It has been demonstrated that individual BMI-increasing variants, particularly in FTO, are associated with higher endometrial cancer risk." (PMID 26134033, 2015). "Genetically predicted BMI remained associated with higher risk of endometrial cancer after excluding the FTO variant (OR = 3.19, 95% CI = 1.70 to 6.03, P = 3.2×10–4)." (PMID 26134033, 2015). "In a prior study by the Epidemiology of Endometrial Cancer Consortium (E2C2), the rs9939609 A allele at the fat mass and obesity-associated (FTO) locus was associated with endometrial cancer risk, a relation mediated by BMI." (PMID 26606540, 2015). "In the pooled analysis, the FTO rs9939609 AA genotype was associated with an increased risk of endometrial cancer (OR = 1.17; 95% CI: 1.03–1.32; p = 0.01) compared to women with the TT genotype." (PMID 21347432, 2011). "In this pooled analysis of non-Hispanic white women from the United States, Poland, Canada and Australia, we found that carriers of the FTO rs9939609 AA genotype were at increased risk of endometrial carcinoma." (PMID 21347432, 2011). "In case-control analyses, carriers of the FTO rs9939609 AA genotype were at increased risk of endometrial carcinoma compared to women with the TT genotype [odds ratio (OR) = 1.17; 95% confidence interval (CI): 1.03–1.32, p = 0.01]." (PMID 21347432, 2011). "This correlation suggests that elevated FTO levels may be linked to more aggressive disease progression and poorer prognosis in endometrial cancer patients." (PMID 39175477, 2024). "In addition, FTO overexpression has been associated with poor prognosis in breast, thyroid, gastric and endometrial cancer." (PMID 36497402, 2022). "Notably, FTO overexpression is associated with poor prognosis in breast, thyroid, gastric, and endometrial cancer." (PMID 36497402, 2022). "Hence, we supposed that the altered expression and variants of the FTO gene contribute to the progression and prognosis of women with endometrial cancer through energy metabolism as well as IGF1 signaling." (PMID 34149936, 2021). "The BMI-increasing allele at FTO was associated with higher risk of endometrial cancer (OR = 1.16, 95% CI = 1.07 to 1.27, P = 5.6×10–4), which may reflect the larger effect size of FTO variants on BMI than other variants (available online)." (PMID 26134033, 2015). "FTO’s oncogenic potential extends to cervical and endometrial cancers, where it interacts with transcription factors such as E2F1 and MYC to regulate tumor cell proliferation and migration." (PMID 39192357, 2024). "Their research also demonstrated that estrogen enhances FTO mRNA levels in endometrial cancer cells in a dose-dependent manner, with the most pronounced effects occurring at concentrations of 9–10 mol/L." (PMID 39175477, 2024). "Despite these insights, the detailed relationship between variations in the FTO gene and the incidence or progression of endometrial cancer remains poorly understood." (PMID 39175477, 2024). "Patients exhibiting high levels of FTO expression in endometrial cancer tissues tend to have significantly shorter periods of DFS and OS in comparison to those with lower FTO expression." (PMID 39175477, 2024). "m6A demethylase FTO expression can be induced by estrogen in endometrial cancer via activation of the PI3K-Akt and MAPK pathways." (PMID 37270544, 2023).
endometrial cancer (continued). "More recent work by Zhang’s group found that FTO promoted endometrial cancer metastasis by activating the Wnt signaling pathway." (PMID 35628623, 2022). "In particular, FTO expression was constantly abundant in both endometrial cancer specimens and endometrial cancer cell lines." (PMID 35409166, 2022). "Researchers examined the expression of FTO in endometrial tumor tissues, and immunohistochemistry staining showed that FTO was highly expressed in endometrial cancer tissues." (PMID 35628623, 2022). "In endometrial carcinoma (EC), FTO overexpression promoted endometrial cancer proliferation and invasion, through PI3K/AKT and MAPK signaling pathways." (PMID 35409166, 2022). "FTO-mediated tumorigenic role in endometrial cancer was uncovered and connected to the mTOR pathway, while mTOR’s connection to FTO-obesogenic functions awaits further exploration." (PMID 35409166, 2022). "In previous years, the inherent link between FTO and endometrial cancer had also attracted the attention of scientists." (PMID 35628623, 2022). "Thus, FTO may regulate cell cycle-associated genes in the progression of endometrial cancer." (PMID 34149936, 2021). "IGF1 signaling contributes to the regulation of EMT 35, and our result also indicated the potential function of IGF1 in the regulatory role of FTO in endometrial cancer." (PMID 34149936, 2021). "Wnt/β-catenin hyperactivation through FZD7 overexpression, a Wnt receptor, which has its elevation mediated by YTHDF1, leads to GC carcinogenesis and Wnt pathway activation by FTO promotes endometrial cancer." (PMID 34526985, 2021). "We examined the association of FTO rs9939609 and MC4R rs17782313 with endometrial cancer risk in a pooled analysis of nine case-control studies within the Epidemiology of Endometrial Cancer Consortium (E2C2)." (PMID 21347432, 2011). "Unconditional logistic regression models were used to assess the relation of FTO rs9939609 and MC4R rs17782313 genotypes to the risk of endometrial cancer." (PMID 21347432, 2011). "Association of the FTO rs9939609 and MC4R rs17782313 with endometrial carcinoma risk among women with BMI data available." (PMID 21347432, 2011). "Description of the studies included in the pooled analysis of FTO rs9939609 and MC4R rs17782313 and endometrial carcinoma risk." (PMID 21347432, 2011). "These insights reveal a novel aspect of FTO’s role in cancer biology, indicating that its impact on endometrial cancer is not merely a consequence of its association with body weight but involves distinct mechanisms that warrant further investigation." (PMID 39175477, 2024). "Increased FTO expression has also been observed in endometrial cancer tissues." (PMID 39175477, 2024). "In addition, in the case of endometrial cancer, FTO is also found to be changing the TME through regulating matrix metalloproteinase (MMPs), which are key player enzymes in promoting cancer growth." (PMID 34526985, 2021). "FTO, RBM15, and YTHDF1, were identified as independent prognostic markers and closely associated with International Federation of Gynecology and Obstetrics grade in endometrial cancer patients." (PMID 34149936, 2021). "However, it has been shown that FTO is able to regulate MMPs to promote cell migration in the endometrial cancer cell line Ishikawa." (PMID 30730976, 2019). "FTO rs9939609 is a susceptibility marker for white non-Hispanic women at higher risk of endometrial cancer." (PMID 21347432, 2011). "Association of the FTO rs9939609 and MC4R rs17782313 with endometrial carcinoma risk." (PMID 21347432, 2011). "Thus, leading to FTO nuclear localization, and increasing endometrial cancer proliferation." (PMID 35409166, 2022). "Interestingly, the association between FTO and endometrial carcinoma did not consider FTO as an m6A demethylase, since FTOs demethylation activity was not reported until later that same year." (PMID 35409166, 2022).